HERC4 (HECT and RLD domain containing E3 ubiquitin protein ligase 4)
Description:
Probable E3 ubiquitin-protein ligase involved in either protein trafficking or in the distribution of cellular structures. Required for spermatozoon maturation and fertility, and for the removal of the cytoplasmic droplet of the spermatozoon. E3 ubiquitin-protein ligases accept ubiquitin from an E2 ubiquitin-conjugating enzyme in the form of a thioester and then directly transfer it to targeted substrates.
Synonyms: KIAA1593; DKFZP564G092
Tractability: PROTAC: ubiquitination databases record sites on it; its protein half-life has been measured.
Gene: Protein-coding gene on chromosome 10 (67,921,899 to 68,075,342, reverse strand). Ensembl gene ENSG00000148634.
Subcellular location: Cytoplasm, cytosol
Subcellular location (Human Protein Atlas): Cytosol; Nucleoli fibrillar center; Primary cilium; Primary cilium tip
Pathways (Reactome):
Immune System: Antigen processing: Ubiquitination & Proteasome degradation
Gene Ontology:
Molecular function: ubiquitin protein ligase activity; ubiquitin-protein transferase activity
Biological process: negative regulation of smoothened signaling pathway; protein ubiquitination; spermatogenesis; ubiquitin-dependent protein catabolic process
Cellular component: cytosol
Genetic constraint (gnomAD): Loss-of-function variants: 12 observed, 59.06 expected, observed/expected ratio (o/e) 0.2, 90% interval 0.13 to 0.33. The upper end of that interval is the gene's LOEUF score, 0.33, which puts it in group 1 of 6, group 1 being the genes least tolerant of losing a copy. Missense variants: 417 observed, 769.25 expected, observed/expected ratio (o/e) 0.54, 90% interval 0.5 to 0.59. Synonymous variants: 256 observed, 275.67 expected, observed/expected ratio (o/e) 0.93, 90% interval 0.84 to 1.03.
Homologues: Orthologues: chimpanzee HERC4 (99% identical), macaque HERC4 (99% identical), rabbit HERC4 (99% identical), dog HERC4 (98% identical), pig HERC4 (98% identical), mouse Herc4 (97% identical), guinea pig HERC4 (95% identical), rat Herc4 (93% identical), tropical clawed frog herc4 (80% identical), zebrafish herc4 (76% identical). Paralogues in human: HERC3 (56% identical), HERC6 (36% identical), HERC5 (34% identical), HERC2 (27% identical), UBE3A (21% identical), HECW1 (19% identical), HECTD4 (19% identical), HECW2 (19% identical), HECTD2 (18% identical), TRIP12 (18% identical), HECTD1 (17% identical), HUWE1 (17% identical), and 12 more.
Diseases named in the same sentence as HERC4 in open-access papers:
HERC4 is named in the same sentence as 23 diseases in open-access papers, as found by Europe PMC text mining. Sharing a sentence is not in itself a finding about the gene and the disease. The quoted sentences say what the papers report.
breast carcinoma (7 papers, 2013 to 2023). "Therefore, it can be speculated that the high expression of exons corresponding to HerC4 and Ephx2 may be a risk factor for poor prognosis of breast cancer, and may be a more sensitive indicator than the parent gene." (PMID 33020551, 2020). "Although HERC4 is oncogenically overexpressed in several cancers including lung cancer and breast cancer, it is downregulated during the progress of myelomagenesis from health bone marrow, MGUS, SMM to typical MM." (PMID 37028761, 2023). "HERC4 is indicated to promote breast cancer progression via inhibiting tumor suppressor LATS1 via interaction with miRNA." (PMID 35064108, 2022). "In conclusion, this study found that DDX39B, EPHX2 (exo7), and HERC4 (exo23) can be used as potential targets for the treatment of breast cancer, which provides a new idea for the treatment of breast cancer." (PMID 33020551, 2020). "To investigate the roles of HERC4 in breast tumorigenesis, we examined the expression levels of HERC4 mRNA and protein in various breast cancer cell lines." (PMID 30710319, 2019). "Published and our data indicate that the HERC4 gene was overexpressed in human breast cancers and its expression predicts poor prognosis of breast cancer patients." (PMID 30710319, 2019). "When compared to the normal breast epithelial cell line MCF-10A, the expression levels of HERC4 mRNA and protein were increased in breast cancer cell lines such as MDA-MB-231 and MCF-7 cells." (PMID 30710319, 2019). "The overexpression of LATS1 reversed the tumorigenic activities induced by the overexpression of HERC4 in breast cancer cells." (PMID 30710319, 2019). "The E3 ligase HERC4 is overexpressed in human breast cancer and its expression levels correlated with the prognosis of breast cancer patients." (PMID 30710319, 2019). "Here we demonstrate that HERC4 promotes breast cancer progression by destabilizing tumor suppressor LATS1." (PMID 30710319, 2019). "In further support of an important role of HERC4 in the tumorigenesis of breast cancer cells, the knockdown of HERC4 in MCF7 cells significantly reduced the growth of tumors formed by MCF7 cells in immunodeficient mice." (PMID 30710319, 2019). "Here we demonstrate that the knockdown of HERC4 in human breast cancer cells dramatically suppressed their proliferation, survival, migration, and tumor growth in vivo, while the overexpression of HERC4 promoted their aggressive tumorigenic activities." (PMID 30710319, 2019). "Considering the important roles of HERC4 in tumorigenesis, we also investigated the upstream regulators of HERC4 in breast cancers and have identified two miRNAs that suppress the expression of HERC4." (PMID 30710319, 2019). "miRNA-136-5p and miRNA-1285-5p, expression of which is decreased in human breast cancers and is inversely correlated with the prognosis of breast cancer patients, are directly involved in suppressing the expression of HERC4." (PMID 30710319, 2019). "IHC was conducted to investigate the expression pattern of HERC4 in breast cancer and normal breast tissues." (PMID 24225229, 2013). "As for the mechanisms of HERC4 potential regulation of breast cancer cells invasion and migration need further investigation." (PMID 24225229, 2013). "Real-time PCR and western blot analysis were used to detect HERC4 expression in 32 paired breast cancer and adjacent normal breast tissues." (PMID 24225229, 2013). "We evaluated the HERC4 expression in breast cancer cell lines and breast tumor tissues by quantitative real-time PCR and western blot analysis." (PMID 24225229, 2013). "HERC4 interacts with miRNA and induces breast cancer progression via inhibiting LATS1." (PMID 35064108, 2022). "In addition, the protein levels of HERC4 were inversely correlated with the protein levels of LATS1 in breast cancer cells, supporting the notion that HERC4 negatively regulates the protein levels of LATS1." (PMID 30710319, 2019).
breast carcinoma (continued). "In addition, we identified the upstream tumor suppressive miRNAs that suppress breast tumorigenesis by inhibiting the expression of HERC4 in human breast cancer cells." (PMID 30710319, 2019). "Therefore, we examined the roles of HERC4 in these breast cancer cells by knockdown or overexpression of HERC4." (PMID 30710319, 2019). "The overexpression of HERC4 is correlated with the poor prognosis of breast cancer patients." (PMID 30710319, 2019). "In addition, the expression levels of HERC4 were inversely correlated with the prognosis of human breast cancer patients." (PMID 30710319, 2019). "Since miR-1285-3p and miR-136-5p suppress HERC4 expression in breast cancer cells, we predicted that these miRNAs could have the same tumor suppressive effects as the silencing of HERC4." (PMID 30710319, 2019). "Here we report that HERC4 was up-regulated in tumor cells of clinical breast cancer samples." (PMID 24225229, 2013). "Similarly, high expression of HERC4 was founded in clinical breast cancer tissue in comparison with adjacent normal breast tissues." (PMID 24225229, 2013). "The results were in line with expectations that expression of HERC4 is significantly higher in the breast cancer cells than in the adjacent normal breast cells whether on mRNA level or on protein level (P < 0.05)." (PMID 24225229, 2013). "Here we study whether HERC4 expression exsit between breast cancer and adjacent normal breast tissues and its clinicopathological significance in patients with invasive ductal carcinoma." (PMID 24225229, 2013). "HERC4 is up-regulated in breast cancer cell lines and breast tumor tissues." (PMID 24225229, 2013). "To validate our inference, we checked HERC4 expression in 32 paired breast cancer (13 intraductal carcinoma and 19 histologically confirmed invasive ductal carcinoma) and adjacent normal breast tissue samples by quantitative real-time PCR and western blot analysis." (PMID 24225229, 2013). "HERC4 could induce breast cancer progression by downregulating the tumor suppressor LATS110." (PMID 35637966, 2022). "Therefore, HERC4-mediated degradation of LATS1 could represent a major oncogenic pathway in breast cancer." (PMID 30710319, 2019). "Therefore, our aim in this study was to investigate whether HERC4 play a role in the development of breast cancer and clinical significance." (PMID 24225229, 2013). "This suggested that breast cancer cells may have a higher expression level of HERC4." (PMID 24225229, 2013). "For example, HERC1, HERC4, and HERC5 have been found to be overexpressed in human breast cancer and to promote cancer progression." (PMID 35889210, 2022). "We discovered that HERC4 is a new E3 ligase of LATS1 and can destabilize LATS1 in both normal breast epithelial cells and breast cancer cells by inducing the ubiquitination of LATS1." (PMID 30710319, 2019). "Using the expression data of HERC4 in breast tumors and tumor-adjacent normal tissues in the database (GSE 93601), we confirmed that HERC4 was overexpressed in breast cancers." (PMID 30710319, 2019). "Our discovery of the functional link between miRNAs, HERC4 and LATS1 reveals a pathway that plays important roles in human breast tumorigenesis and provides new therapeutic targets for breast cancer treatment." (PMID 30710319, 2019). "Using co-immunoprecipitation (CO-IP) assay, we confirmed the interaction between HERC4 and LATS1 in breast cancer cells." (PMID 30710319, 2019). "The result showed that HERC4 was up-regulated in nearly all breast cancer cell lines compared to non-tumorigenic breast epithelial cell line MCF-10A, suggesting higher expression of HERC4 exists in tumor cells of clinical breast cancer samples." (PMID 24225229, 2013). "HERC4 was up-regulated in breast cancer cell lines and breast tumor tissues compared to non-tumorigenic cell line and adjacent normal breast tissues." (PMID 24225229, 2013).
lung carcinoma (4 papers, 2019 to 2025). "In support of this notion, the published pathological studies have indicated that HERC4 is associated with several types of malignant cancers such as lung cancer and hepatic cancer." (PMID 30710319, 2019). "HERC4, an E3 ubiquitin ligase involved in DNA damage repair, cellular growth, and immune regulation, has previously been associated with cancers including breast and lung cancer." (PMID 40856249, 2025). "For example, HERC4 is believed to contribute to carcinogenesis of solid tumors such as lung cancer, but it suppresses the proliferation of myeloma cells." (PMID 32724061, 2020). "Since HERC4 is also frequently overexpressed in human lung cancers, we also studied the roles of HERC4 in human lung cancer cell line A549." (PMID 30710319, 2019). "The knockdown of HERC4 in A549 lung cancer cells also suppressed their cellular proliferation, migration and survival." (PMID 30710319, 2019). "HERC4 is overexpressed in several types of cancer such as lung cancer and hepatocellular carcinoma." (PMID 30710319, 2019). "In addition, our data also indicate that HERC4 promotes the tumorigenesis of human lung cancer cells." (PMID 30710319, 2019).
myeloma (3 papers, 2020 to 2024). "The existing study has confirmed that HERC4 is involved in inhibiting the proliferation of myeloma cells." (PMID 38898455, 2024). "The combo treatment strikingly upregulated HERC4 and MafA in the myeloma xenografts compared with the control or the single treatments." (PMID 37028761, 2023). "This is confirmed by the combined treatment of LiCl, the inhibitor of GSK3β, and Dex, a major anti-MM agent, which strikingly upregulate HERC4 and inhibit MafA therefore suppressing MM cell proliferation and myeloma xenograft growth in mice." (PMID 37028761, 2023). "In the present study, we found that inhibition of GSK3β and induction of HERC4 might inhibit MafA and suppress myeloma cell proliferation and tumor growth." (PMID 37028761, 2023).
Infertility (2 papers, 2019 to 2022). "Several CDK2-bound genes have also been implicated in other aspects of germ cell development, including Palb2, Pds5b, Safb1, and Herc4, or have been investigated as potential markers of infertility in human populations: Mtrr and Vdac3." (PMID 31350280, 2019).
invasive ductal breast carcinoma (2 papers, 2013 to 2015). The most common type of invasive breast carcinoma, accounting for approximately 70% of breast carcinomas. "Our findings suggest that HERC4 was a significant diagnostic marker for invasive ductal carcinoma of the breast." (PMID 24225229, 2013). "Taken together, our result indicated that HERC4 could be used as a significant diagnostic marker for invasive ductal carcinoma." (PMID 24225229, 2013). "Positive expression of HERC4 was positively correlated with pT status, pN status, clinical stage and histological grade of patients with invasive ductal carcinoma (p < 0.05)." (PMID 24225229, 2013). "The expression of HERC4 in invasive ductal carcinoma was positively related to the clinical stage, histological grade and pT status." (PMID 24225229, 2013). "Positive expression of HERC4 was positively correlated with invasive ductal carcinoma pT status, pN status, clinical stage and histological grade (p < 0.05)." (PMID 24225229, 2013). "In addition, Herc4 was found to be upregulated in over half of a cohort of invasive ductal breast carcinoma." (PMID 26125558, 2015). "On the basis of cut-off score, HERC4 positive expression was detected in 1/16 (6.3%) of normal breast tissue, in 3/13 (23.1%) of fibroadenoma, in 6/15 (40%) of intraductal carcinoma and 66/120 (55%) of invasive ductal carcinoma (p < 0.05, χ2-test)." (PMID 24225229, 2013). "According to ROC analysis, HERC4 positive expression was detected in 1/16 (6.3%) of normal breast tissue, in 3/13 (23.1%) of fibroadenoma, in 6/15 (40%) of intraductal carcinoma and 66/120 (55%) of invasive ductal carcinoma." (PMID 24225229, 2013). "Furthermore, to assess clinicopathological significance of HERC4, we performed immunohistochemical analysis on a tissue microarray containing 13 benign fibroadenoma, 15 intraductal carcinoma, 120 histologically confirmed invasive ductal carcinoma and 16 adjacent normal breast tissue samples." (PMID 24225229, 2013).
endometriosis (1 paper, 2022). The growth of functional endometrial tissue in anatomic sites outside the uterine body. "We next analyzed the expression levels of SOX4, PGR, FOXO1, HERC4, IGFBP1, and PRL in the mid-secretory endometrium of healthy women (control, n = 12) versus women who suffered RIF due to endometriosis (EMS-RIF, n = 12)." (PMID 35244538, 2022).
glioblastoma (1 paper, 2025). The most malignant astrocytic tumor (WHO grade IV). "For example, DHODH is a downstream regulator of PRR11, which maintaining DHODH protein stability by inhibiting the binding between E3 ubiquitin ligase HERC4 and DHODH in glioblastoma." (PMID 40715045, 2025).
hepatocellular carcinoma (1 paper, 2023). A malignant tumor that arises from hepatocytes. "The overexpression of HERC4 facilitates the proliferation of hepatocellular carcinoma (HCC), whereas depletion of HERC4 slows down proliferation and increases the apoptotic rate of HCC." (PMID 37465127, 2023).
late-onset Alzheimers disease (1 paper, 2014). This is the most common form of the disease, which happens to people age 65 and older. "Other genes mapping in the deleted region, including DNAJC12 (MIM 606060), HERC4 (MIM 609248), PBLD (MIM 612189), HNRNPH3 (MIM 602324), RUFY2 (MIM 610328), STOX1 (MIM 609397), and CTNNA3 (MIM 607667), have been linked to late-onset Alzheimer’s disease (AD6; MIM 605526)." (PMID 24297458, 2014).
parasitic infection (1 paper, 2023). "On the other hand, parasitic infection decreased sperm quality and downregulated the expression levels of Herc4, Ipo11, and Mrto4, and these genes were strongly related to spermatogenesis." (PMID 36982803, 2023). "In order to assess the relationship between parasitic infection and testicular spermatogenic function, we determined the gene expression levels of Herc4, Ipo11, and Mrto4 by qRT-PCR." (PMID 36982803, 2023).
Trichinella spiralis infection (1 paper, 2023). "Consistent with previous studies, Trichinella spiralis infection decreased the sperm quantity and quality, and the expression levels of genes related to spermatogenesis were also suppressed including Herc4, Ipo11, and Mrto4." (PMID 36982803, 2023). "Trichinella spiralis infection downregulated the gene expression levels of Herc4, Mrto4, and Ipo11, genes closely related to the production and functional expression of sperm, which led to the decrease in sperm count." (PMID 36982803, 2023).
vitiligo (1 paper, 2025). Generalized well circumscribed patches of leukoderma that are generally distributed over symmetric body locations and is due to autoimmune destruction of melanocytes. "We identified seven proteins (HEPHL1, PRDX1, DEFA1, CSGALNACT2, HERC4, NDC80, and SPHK2) causally associated with vitiligo risk." (PMID 40856249, 2025). "Our integrative MR analysis identified novel protein biomarkers and promising therapeutic targets for vitiligo, particularly HERC4 and NDC80." (PMID 40856249, 2025). "Similarly, HERC4 regulates immune signaling, cell growth, and protein degradation, which may impact keratinocyte function and contribute to immune dysregulation in vitiligo." (PMID 40856249, 2025). "Taken together, these findings suggest that both HERC4 and NDC80, through their roles in immune modulation, oxidative stress, and cell survival, likely contribute to vitiligo pathogenesis by altering keratinocyte‐melanocyte interactions." (PMID 40856249, 2025). "We identified the elevated expression of HERC4 and NDC80 in vitiligo‐affected skin compared to healthy controls (p < 0.05) using the GEO dataset (GSE65127)." (PMID 40856249, 2025). "Notably, HERC4 and NDC80 exhibited robust expression in vitiligo lesions across validation datasets." (PMID 40856249, 2025). "In addition, analysis of the GEO dataset (GSE65127) identified the significant upregulation of HERC4 and NDC80 in vitiligo lesions." (PMID 40856249, 2025).
cancer (7 papers, 2013 to 2025). A tumor composed of atypical neoplastic, often pleomorphic cells that invade other tissues. "Given their consistent down-regulation, and the fact that FADS2 was found down-regulated after combinational treatment of selinexor and carfilzomib, we tested whether FADS2 and HERC4 play a role in carfilzomib’s anti-cancer effects." (PMID 32851475, 2021). "Since HERC4 and LATS1 genes are ubiquitously expressed, our findings suggest that HERC4 could have broad oncogenic activity in various human cancers." (PMID 30710319, 2019). "However, in human cancer biology, the physiological substrates and biological functions of HERC4 are unknown." (PMID 24225229, 2013). "The previous research reported that IFIT1, IFIT2, IFTI3, IFIT3, IFI44, HERC4, and OASL genes are antitumoral effects and modulated the inflammatory response in cancer and infection." (PMID 35941292, 2022). "However, the expression status and biological functions of HERC4 in cancers are not clearly." (PMID 24225229, 2013).